IGFBP2 (insulin like growth factor binding protein 2)
Diseases named in the same sentence as IGFBP2 in open-access papers (continued):
Sharing a sentence is not in itself a finding about the gene and the disease.
hepatoblastoma (2 papers, 2005 to 2020). Hepatoblastoma (HB) is a malignant hepatic tumor and is the most common pediatric liver cancer. "The IGFBP3 levels were very low or undetectable in human HCC samples compared with non‐neoplastic liver tissue which are 4‐ to 100‐fold higher than in HCC49 and IGFBP‐1 and IGFBP‐2 were also decreased in hepatoblastoma." (PMID 32798252, 2020).
HIV-1 infection (2 papers, 2017 to 2022). The type species of lentivirus and the etiologic agent of acquired immunodeficiency syndrome (AIDS). "For example, IGFBP2 expression was downregulated by humanization, upregulated by HIV-1 infection and is associated with inflammatory responses in HIV-1-infected patients." (PMID 29084769, 2017). "They observed the upregulation of CXC3R1, ITAC, IGFBP-2, TECK, TRAIL-R4, and MIP-1α in CD4+ and CD8+ T cells and monocytes during the aviremic phase of follow-up, indicating a potential role in viral control during HIV-1 infection." (PMID 35844607, 2022).
hypothyroidism (2 papers, 2012 to 2018). Abnormally low levels of thyroid hormone. "In this work, several biomarkers of neonatal hypothyroidism (i.e., decreased circulating THs and hepatic mRNA expression levels of ME and Spot14) and high expression of IGFBP-2 were associated with decreased circulating IGF-I and a delayed somatic growth rate on PND30." (PMID 22666351, 2012). "Low Igfbp2 expression has been reported in hypothyroidism and its increase in expression is likely due to a feedback mechanism following increased serum T4." (PMID 29883366, 2018). "Subtle changes in hepatic IGF-I and IGFBP-3 mRNA levels together with increased levels of IGFBP-2, a gene that is a marker of delayed development or hypothyroidism in rats, were also shown on PND80." (PMID 22666351, 2012).
invasive breast carcinoma (2 papers, 2010 to 2020). A carcinoma that infiltrates the breast parenchyma. "A recent study from a large series of primary invasive breast cancers showed that tumor expression of IGFBP2 was a positive predictor of overall survival in a multivariate analyses adjusted for BMI, and its expression correlated with estrogen receptor status." (PMID 32133294, 2020).
ischemia (2 papers, 2018 to 2024). A hypoperfusion of the BLOOD through an organ or tissue caused by a PATHOLOGIC CONSTRICTION or obstruction of its BLOOD VESSELS, or an absence of BLOOD CIRCULATION. "Thus, IGFBP2 may serve as a promising novel biomarker of AKI, and Res-NPs may prevent kidney injury from ischemia/reperfusion in a rat model." (PMID 30564296, 2018).
kidney damage (2 papers, 2012 to 2018). "Our data indicated that the level of IGFBP2 can better reflect timely the renal injury than traditional serum biomarkers (BUN, CRP, Cys-C, and SCr), indicating that IGFBP2 exhibits a good sensitivity for kidney damage." (PMID 30564296, 2018).
Liver Cirrhosis (2 papers, 2023 to 2024). "After excluding patients with liver cirrhosis and adiposity, the association of serum IGFBP-2 and survival was not significant (p = 0.096)." (PMID 38255230, 2024).
melancholic depression (2 papers, 2016 to 2019). "Serum IGFBP-2-protein and -mRNA expression was downregulated in patients with bipolar disease, and serum IGFBP-2 protein levels were lower in patients with atypical and melancholic depression than in controls." (PMID 31824433, 2019).
memory impairment (2 papers, 2022 to 2025). "Based on this anatomical evidence, we then selectively modulated Igfbp2 expression in these projection‐specific PVT glutamatergic neurons to determine its causal role in anesthesia‐induced memory impairment." (PMID 40801458, 2025). "To further explore the impact of Igfbp2 on anesthesia‐induced memory impairment, we injected AAV‐CMV‐DIO‐shRNA (Igfbp2)‐eYFP (AAV‐shRNA) or the scramble virus AAV‐CMV‐DIO‐shRNA (scramble)‐eYFP (AAV‐scramble) into the PVT of Vglut2‐Cre control mice." (PMID 40801458, 2025). "IGFBP2 plays an essential role in cognitive development during early life, it is a potential target for learning and memory impairment therapies and neurodegenerative diseases." (PMID 35203526, 2022). "Using cue fear conditioning tests, thalamic fos mapping, in vivo fiber photometry, ex vivo whole‐cell recordings, optogenetics and transcriptomic sequencing, we identified a critical role of Igfbp2 within the PVT glutamatergic neurons in regulating anesthesia‐induced memory impairment." (PMID 40801458, 2025).
nephritis (2 papers, 2021 to 2022). Inflammation of renal tissue. "More experiments are needed to reveal the in-depth pathogenic mechanism of IGFBP2 in nephritis and its regulatory effect on other immune cells." (PMID 36008635, 2022). "Studies of IGFBP-2 focused in secondary nephritis caused by autoimmune disease." (PMID 35002740, 2021). "In some studies, serum IGFBP-2 level is correlated positively with serum creatinine and can be used as a marker of to reflect the activity and chronic degree of nephritis." (PMID 35002740, 2021). "We demonstrated neutralizing IGFBP2-downregulated CD4+ T cell activation, upregulated the ratio of Treg, downregulated AKT/mTOR/4E-BP1 pathway, and significantly improved nephritis in MRL/lpr mice." (PMID 36008635, 2022).
osteoporosis (2 papers, 2019 to 2025). A condition of reduced bone mass, with decreased cortical thickness and a decrease in the number and size of the trabeculae of cancellous bone (but normal chemical composition), resulting in increased fracture incidence. "It is important to note that an increase of 100 standard deviations in IGFBP-2 levels decreased the risk of developing osteoporosis by 20%." (PMID 41305735, 2025). "Importantly, this causal relationship between IGFBP-2 and osteoporosis remained in initial practice using the adjusted P-values (P < .007) after Bonferroni correction, which reinforced the validity of our conclusions." (PMID 41305735, 2025). "In addition, this causal relationship between IGFBP-2 and osteoporosis remained in initial practice using the adjusted P-values (P < .007) after Bonferroni correction, which reinforced the validity of our conclusions." (PMID 41305735, 2025). "High-quality RCT studies are still needed in the future to clarify the relationship between IGFBP-2 and osteoporosis." (PMID 41305735, 2025). "Based on the IVW results, we identified a causal relationship between IGFBP-2 and osteoporosis, in which IGFBP-2 prevented the development of osteoporosis (IVW, P = .006; odds ratio = 0.998; β = −0.0022; 95% confidence interval: 0.996–0.999)." (PMID 41305735, 2025). "Based on the IVW obtained, we observed a negative causal relationship between IGFBP-2 and osteoporosis (IVW: P = .006; odds ratio [OR] = 0.998; β = −0.0022; 95% confidence interval [CI]: 0.996–0.999)." (PMID 41305735, 2025). "This suggested that IGFBP-2 had a preventive effect on the development of osteoporosis." (PMID 41305735, 2025). "This MR study suggests a potential protective role of IGFBP-2 against osteoporosis and that it may serve as a biomarker or therapeutic target, although further research is needed." (PMID 41305735, 2025). "In summary, this MR study suggests a potential protective role of IGFBP-2 against osteoporosis and that it may serve as a biomarker or therapeutic target, although further research is needed." (PMID 41305735, 2025). "The study successfully demonstrated a negative causal link between IGFBP-2 and osteoporosis, evidence which may contribute to prevention and early intervention in individuals with a high risk of developing osteoporosis." (PMID 41305735, 2025). "The results indicate a negative correlation between IGFBP-2 and the development of osteoporosis, suggesting that higher concentrations of IGFBP-2 may be associated with a reduced risk of osteoporosis." (PMID 41305735, 2025). "Notably, although the effect size (β = −0.0022) between IGFBP-2 and osteoporosis seems not large, it indicates that an increase of 100 standard deviations in IGFBP-2 levels decreased the risk of developing osteoporosis by 20%." (PMID 41305735, 2025).
pterygium (2 papers, 2009 to 2020). A wedge-shaped fibrovascular lesion arising from the bulbar conjunctiva and extending to the cornea. "IGFBP-2 has also been linked to cellular overgrowth in pterygium." (PMID 32194500, 2020). "Microarray comparisons of pterygium and conjunctiva-derived fibroblasts found evidence for increased expression of insulin-like growth factor-binding protein 2 in pterygium." (PMID 19956562, 2009). "Using cDNA microarrays, IGFBP-2 expression was increased in fibroblasts cultured from the pterygium body compared to conjunctival fibroblasts collected from normal tissue." (PMID 32194500, 2020).
renal failure (2 papers, 2023 to 2024). "This suggests that elevated plasma IGFBP-2 levels in patients with septic shock correlate with disease severity, rather than specific kidney failure." (PMID 38137505, 2023).
serous ovarian carcinomas (2 papers, 2005 to 2020). "Furthermore, IGFBP2 was significantly overexpressed in invasive serous ovarian carcinomas compared with borderline serous ovarian tumors." (PMID 15686601, 2005).
small cell lung carcinoma (2 papers, 2014 to 2015). Small cell lung cancer (SCLC) is a highly aggressive malignant neoplasm, accounting for 10-15% of lung cancer cases, characterized byrapid growth, and early metastasis. "In 11 out of 12 primary small cell lung cancer tissues assessed, the IGFBP-2 promoter was present in an unmethylated form, which confers higher gene expression in comparison with other histological subtypes." (PMID 24778626, 2014). "In small cell lung cancer cell lines, a proximal E-box was identified that binds NeuroD and thereby induces IGFBP-2 expression." (PMID 24778626, 2014).
triple-negative breast carcinoma (2 papers, 2023 to 2024). An invasive breast carcinoma which is negative for expression of estrogen receptor (ER), progesterone receptor (PR), and human epidermal growth factor receptor 2 (HER2). "After examining the impact of IGFBP-2 on DNA damage induced by etoposide in estrogen-receptor-positive breast cancer cells, the study extended its investigation to triple-negative breast cancer cells (TNBC), characterised by the absence of ER, PR, and HER2 (a member of the EGFR family)." (PMID 38893232, 2024).
3M syndrome (1 paper, 2017). 3M syndrome is a primordial growth disorder characterized by low birth weight, reduced birth length, severe postnatal growth restriction, a spectrum of minor anomalies (including facial dysmorphism) and normal intelligence. "In addition, alterations in IGFBP-2 and IGFB5 messenger ribonucleic acid levels were previously documented to be associated with OBSL1 mutations in cases with 3M syndrome diagnoses." (PMID 27796265, 2017).
abnormal glucose tolerance (1 paper, 2022). An abnormal resistance to glucose, i.e., a reduction in the ability to maintain glucose levels in the blood stream within normal limits following oral or intravenous administration of glucose. "After adjustment, the lowest quartile of adiponectin, IGFBP-1 and IGFBP-2 associated independently with future abnormal glucose tolerance (AGT) in both genders in multivariate analyses." (PMID 36686443, 2022).
Acute encephalopathy (1 paper, 2021). "Furthermore, these results implicate serum IGFBP2 level as a potential marker of disease activity in patients with HUS and acute encephalopathy." (PMID 33641616, 2021).
Alström syndrome (1 paper, 2009). "Free IGF1, IGFBP-1 were significantly reduced and IGFBP-2 was markedly increased in all 3 patients compared to age-matched controls, which points to a growth hormone deficiency (GHD) condition in Alstrom syndrome." (PMID 19128470, 2009).
anaplastic oligodendroglioma (1 paper, 2016). A WHO grade III oligodendroglioma with focal or diffuse malignant morphologic features (prominent nuclear pleomorphism, mitoses, and increased cellularity). "Our gene signature also contained proneural genes, BMP2, DCX, IGFBP2, PDPN, and PLAT, which are associated with anaplastic oligodendroglioma harboring 1p/19q co-deletion." (PMID 27323413, 2016).
angina (1 paper, 2023). "Furthermore, incidences of angina (p = 0.003) and HF (p = 0.011) were higher among high IGFBP-2 group patients as compared to low IGFBP-2 group patients." (PMID 36970368, 2023).
aortic aneurysm (1 paper, 2024). A ruptured aneurysm located in the wall of the proximal portion of the descending aorta proceeding from the arch of the aorta. "Finally, immunostaining on human aortic aneurysms showed increased TNFRSF11B and IGFBP2 proteins in TAAs relative to AAAs, validating the bioinformatic analysis performed on mouse tissues." (PMID 39590192, 2024).
Arterial thrombosis (1 paper, 2024). The formation of a blood clot inside an artery. "Thirdly, while ROTEM functional tests were conducted to assess how IGFBP-2 inhibition affects ex vivo clot formation and lysis, this technique primarily mirrors the generation of static, low-flow thrombi, which aligns more closely with venous conditions rather than arterial thrombosis." (PMID 38673963, 2024).
ataxia telangiectasia (1 paper, 2014). Ataxia-telangiectasia is the association of severe combined immunodeficiency (affecting mainly the humoral immune response) with progressive cerebellar ataxia. "Both types of patients have increased serum IGF-1 and IGFBP-2 levels, and decreased serum IGFBP-1 levels; while only ataxia-telangiectasia patients have high serum insulin levels." (PMID 26331037, 2014).
atrial fibrillation (1 paper, 2023). A disorder characterized by an electrocardiographic finding of a supraventricular arrhythmia characterized by the replacement of consistent P waves by rapid oscillations or fibrillatory waves that vary in size, shape and timing and are accompanied by an irregular ventricular response. "Five feature m6A regulatory genes, ZC3H13, YTHDF1, HNRNPA2B1, IGFBP2, and IGFBP3, were determined (p < 0.05) to establish a nomogram model that can predict the incidence of atrial fibrillation with the RF model." (PMID 37435047, 2023).
Atrophy (1 paper, 2018). Any weakening or degeneration, especially through lack of use. "We provide statistical evidence that the association between CSF IGFBP-2 and entorhinal, parahippocampal, inferior temporal, and temporal pole atrophy may be related to intracerebral tau (estimated using CSF tau levels)." (PMID 30061810, 2018).
bladder tumours (1 paper, 2019). "These are interesting observations but a comprehensive study of IGFBP-2 in bladder tumours and its association with chemosensitivity and progression is required to fully understand these effects." (PMID 31903164, 2019).
Blindness (1 paper, 2015). Blindness is the condition of lacking visual perception defined as a profound reduction in visual perception. "Ocular localization of the proteins that showed significantly higher expression in the vitreous than in blood (CCL2, IGFBP2, MMP10, HGF, TNFRSF11B) was investigated in histological specimens of eyes from patients with painful blindness due to secondary glaucoma after CRVO." (PMID 25978399, 2015).
bone fracture (1 paper, 2020). "The decrease in IGFBP2 could have dual side effects on both growth stunting and risk of bone fracture." (PMID 33053810, 2020).
breast disease (1 paper, 2015). "Furthermore, a multiantigen vaccine targeting Neu, IGFBP-2 and IGF1R was highly effective at preventing tumor progression in mice with preinvasive breast disease, whereas an individual vaccine was partially effective." (PMID 26173023, 2015).
cervical intraepithelial neoplasia (1 paper, 2015). "In order to establish the clinical relevance of our findings, expression of IGFBP2 was assessed in pre-malignant cervical intraepithelial neoplasia’s (CIN) by immunohistochemistry and dual immunofluorescence, utilising p16INK4A (p16) staining to distinguish premalignant cells from normal cells." (PMID 26107517, 2015).
co-infection (1 paper, 2024). "In our patient cohort, bacterial co-infection was not related to a change in serum IGFBP-2 levels." (PMID 38255230, 2024).
colitis (1 paper, 2019). Inflammation of the colon. "Additionally, both decreased IGFBP3 and increased IGFBP2 levels were found in the colitis group, and the levels of two binding proteins were significantly correlated with calprotectin." (PMID 31221091, 2019). "At d3 and d5, the plasma IGFBP2 concentrations were significantly different among the three groups (F = 19.90, P < 0.001; F = 15.80, P < 0.001) and were significantly higher in both the colitis and pair-fed groups than those in the control group (P < 0.05)." (PMID 31221091, 2019). "Additionally, the rats in the pair-fed group had significantly higher IGFBP2 concentrations than those in the colitis group (P < 0.05)." (PMID 31221091, 2019).
craniosynostosis (1 paper, 2011). Craniosynostosis is defined as the premature fusion of one or more cranial sutures leading to secondary distortion of skull shape resulting in skull deformities with a variable presentation. "Finally, identification of ECM-mediated focal adhesion as a candidate network biomarker also substantiates the identification of VCAM1 and IGFBP2 as potential individual gene biomarkers for craniosynostosis." (PMID 22028906, 2011).
cyst (1 paper, 1996). A sac-like closed membranous structure that may be empty or contain fluid or amorphous material. "Our data suggest that increased local production by the tumour in vivo is responsible for the increased IGFBP-2 levels in the cyst fluid bathing the ovarian malignancy." (PMID 8624265, 1996).
cystic fibrosis (1 paper, 2017). Autosomal recessive disorder caused by pathogenic variants in the CFTR gene (cystic fibrosis transmembrane conductance regulator), which encodes a chloride and bicarbonate channel expressed in epithelial cells, and follow the diagnosis criteria. "We found that IFI16, CCNE2 and IGFBP2 are potential modifiers in the altered lung function in Cystic Fibrosis." (PMID 28339466, 2017).
diabetic retinopathy (1 paper, 2023). "It is important to note that further mechanistic studies are necessary to fully elucidate the precise roles of these immune cell types and their interactions with COL6A3 and IGFBP2 in the development and progression of diabetic retinopathy." (PMID 38124748, 2023). "Therefore, IGFBP2 may influence neovascularization in diabetic retinopathy through modulating VEGF activity mediated by IGF1." (PMID 38124748, 2023).
dilatation (1 paper, 2021). "Of these, IGFBP-2, PSG4, and LXN levels in plasma were independent of cervical dilatation." (PMID 33857242, 2021).
Ductal Carcinoma (1 paper, 2013). "Towards this we performed IHC on 38 grade III Invasive Ductal Carcinoma tissues for β-catenin and IGFBP2 expression." (PMID 23767917, 2013).
dyslipidaemia (1 paper, 2025). "For example, the association of the inflammatory biomarkers MIF and WBCs with AA‐induced dyslipidaemia, as well as the metabolic proteins asprosin, IGFBP‐2, and APOA1 highlight potential areas for further research." (PMID 41017289, 2025).
encephalomyelitis (1 paper, 2019). Inflammation of the brain and the spinal cord. "In addition, the induction of encephalomyelitis in rats resulted in enhanced expression of IGFBP-2 and IGF-I in astrocytes and coincided with remyelination by targeting promyelinating oligodendrocytes." (PMID 31824433, 2019). "In addition, during encephalomyelitis, IGFBP-2 expression in reactive astrocytes targets oligodendrocytes, expressing IGF-I and IGF-IR, which are responsible for remyelination." (PMID 31824433, 2019).